ROS1 (ROS proto-oncogene 1, receptor tyrosine kinase)
Diseases named in the same sentence as ROS1 in open-access papers (continued):
Sharing a sentence is not in itself a finding about the gene and the disease.
tumor (continued). "In this article, we review the current state of molecular diagnostics for ROS1-positive NSCLC, discuss our experience with the relevant technologies and provide guidance on the detection of ROS1-positive tumours." (PMID 27535289, 2016). "Nevertheless, only ten cases with diffuse 2–3+ tumor cytoplasmic reactivity were confirmed as ROS1 rearrangement when FISH was set as the standard method." (PMID 27488371, 2016). "Thirty z-stacks were also optimal to scan CTC FISH spots in patients with a ROS1-rearranged tumor (91 % detection rate)." (PMID 27417942, 2016). "AP-MS has been successfully used to discover novel TKFs in NSCLC (ALK and ROS1) and rare TKFs in other tumor histotypes." (PMID 26943776, 2016). "Tumor tissue specimens were collected and analyzed for ROS1 gene rearrangement using fluorescence in situ hybridization (FISH) and ROS1 protein expression using immunohistochemistry (IHC)." (PMID 26475437, 2015). "Reflecting upon the incidences of ROS1 rearrangements found in other tumor types, it is a rare phenomenon that requires large-scaled screening efforts." (PMID 26366867, 2015). "PD-1 positive tumor infiltrating lymphocytes and PD-L1 expressing tumor cells were seen in 18 of 42 cases (43%) of which 8 cases lacked other biologic targets including EGFR mutations, HER2, cMET, ALK, or ROS1 rearrangements." (PMID 25941796, 2015). "Our data indicate that MassARRAY-based multiplex genetic testing both for somatic mutations and for ALK, ROS1, and RET fusion genes performed well with nucleic acid (DNA and RNA) extracted from FFPE tumor specimens obtained from patients with advanced NSCLC." (PMID 24810493, 2014). "ROS1 IHC-reactive tumors, especially when the tumor is stained with moderate to strong intensity or a diffuse pattern, are recommended to undergo FISH to confirm the gene rearrangement." (PMID 25058391, 2014). "ROS1, a proto-oncogene expressed in various tumor cell lines, is a cellular signaling transduction pathway regulator that mediates cell proliferation, migration and cell-to-cell communication." (PMID 23292247, 2013). "To accomplish this, we analyzed tumor samples from a patient who initially responded to the ROS1 inhibitor crizotinib but eventually developed acquired resistance." (PMID 24349229, 2013). "Analysis of five LADC cases of never-smokers without EGFR/KRAS/ALK alterations using transcriptome sequencing identified 56 reads overriding the in-frame EZR-ROS1 gene fusion point connecting EZR exon 10 to ROS1 exon 34 in one tumor." (PMID 23418494, 2013). "This is consistent with observation that both LMP tumours harbor allelic imbalance of the chr6q arm which include the ROS1, DCBLD1, and GOPC loci." (PMID 22163003, 2011). "Notably, we analyzed three different subgroups of mouse IHG-related models, driven by ALK, NTRK and ROS1, respectively, which have previously been stratified into the same tumor category." (PMID 41381884, 2026). "Two cases have been documented where the tumor exhibited a ROS1 rearrangement." (PMID 40575627, 2025). "We speculate that the estrogen environment within the female body may provide a more favorable microenvironment for the occurrence of ROS1 rearrangement or for the survival of tumor cells driven by ROS1 rearrangement." (PMID 41179684, 2025).
tumor (continued). "From a pathogenetic point, gene fusions between the 5′ of partner genes, including CD74, EZR, GOPC (depending on the neoplasm), and the 3′ regions of ROS1 often play a pivotal role in the activation of cellular survival and growth signaling pathways, leading to oncogenesis." (PMID 40847660, 2025). "CUTO and HCC-78 cell lines cluster separately from ROS1+ NSCLC tumor samples." (PMID 39737401, 2024). "In addition, resistance to ROS1 inhibitors can lead to the phenotypic transformation of tumor cells." (PMID 38629293, 2024). "In addition, our previous study demonstrated that micropapillary LUAD has a significantly higher tumor mutation burden, such as EGFR mutations and ROS1 fusions." (PMID 39188060, 2024). "Targeted inhibitors directed against specific mutated or rearranged oncogenes, such as epidermal growth factor receptor (EGFR), anaplastic lymphoma kinase (ALK), and receptor tyrosine kinase ROS proto-oncogene 1(ROS1) among others, exhibit promising anti-tumor activity." (PMID 39055566, 2024). "In addition, a remarkable heterogeneity in disease outcomes and metastatic patterns is typically observed among patients, highlighting the need for a deeper understanding of the ROS1+ NSCLC tumor biology." (PMID 39737401, 2024). "Additional biomarker analyses were conducted to determine whether there is a relationship between changes in ctDNA levels, as measured by ROS1 fusion levels and cTF, and tumor response over the duration of treatment." (PMID 38898120, 2024). "Moreover, we report differences in oncogene expression such as MYC, MET and BRAF between ROS1+ tumor samples and cell lines, which should be taken into account when interpreting in vitro experiments." (PMID 39737401, 2024). "In addition, administration of a FAK inhibitor promoted the anti-tumor effect of ROS1 inhibitors for both original and crizotinib-resistant CDH1-deficient cancer cells." (PMID 37324948, 2023). "Panitumumab with ROS1-TKIs prevents MIG6-knockout tumor regrowth in vivo." (PMID 37917191, 2023). "During his recovery, molecular testing on the biopsy reported a ROS1 fusion identified by fluorescence in situ hybridization (FISH), and next-generation sequencing (NGS) of tumor DNA identified a KRAS p.G12C mutation and a telomerase reverse transcriptase (TERT) promoter mutation (c.-124C>T)." (PMID 36690705, 2023). "We tested if pharmacological treatment with ROS1 TKI could attenuate the tumor growth driven by ROS1D2113N." (PMID 37587872, 2023). "ROS1 rearrangements result in the expression of the ROS1 fusion oncoprotein, constitutive ROS1 kinase activity, and aberrant downstream signaling activation, ultimately leading to dysregulated tumor survival and proliferation." (PMID 37923925, 2023). "Therefore, our data suggest that ROS1D2113N drives tumor formation that can be attenuated or blocked with ROS1‐TKI, in vivo, supporting the data from cell‐based in vitro models." (PMID 37587872, 2023). "We performed a pan-tumor analysis of the incidence of ROS1 fusions to assess if more ROS1+ patients who could benefit from ROS1 TKIs could be identified." (PMID 37853341, 2023). "In the present study, we tested this hypothesis and found that co-treatment with ROS1 inhibitors and FAK inhibitors conferred synergistic anti-tumor effects in CDH1-deficient mice model of DGC in vitro and in vivo." (PMID 37324948, 2023). "Here, we investigated whether growth factors produced in the tumor microenvironment can induce resistance to entrectinib in tumor cells with NTRK1 or ROS1 rearrangements." (PMID 36416133, 2023).
tumor (continued). "Combining independent risk factors from multivariate analysis, including ROS1 gene mutations, KRAS gene mutations, tumor stage, and endocrine system disease history, a new Nomogram was constructed to predict the therapeutic efficacy of ICIs immunotherapy in PD-L1 positive patients." (PMID 37468609, 2023). "However, one positive case affecting the specificity value had weak positive cytoplasmic staining in 5% of tumor cells and the case had ROS1 gene fusion." (PMID 37374289, 2023). "The loss of ROS1 expression in the resistant tumor—while concordant with phenotypic lack of sensitivity to ROS1 TKI—raises important questions about the continued molecular changes involving the original oncogenic driver during targeted therapy." (PMID 37923925, 2023). "TRK and ROS1 fusion proteins constitutively activate tyrosine kinases and continue to emit survival and proliferation signals, resulting in overgrowth and prolonged survival of tumor cells." (PMID 36416133, 2023). "Globally, there have been additional efforts to target either ALK or ROS1 in rare tumor types." (PMID 35233056, 2022). "We previously reported the fabrication of pH-responsive strontium sulfite nanoparticles (SSNs) and the application of the nanocarrier to efficaciously transport ROS1 siRNA into tumour cells, demonstrating a significant reduction in tumour volume in a murine breast cancer model." (PMID 36412852, 2022). "There was a relatively large proportion of patients with unknown EGFR, ALK and ROS1 status in both cohorts and the tumour PD-L1 expression was unknown for many patients in the Post-1L IO cohort." (PMID 36139641, 2022). "Recently, it has been reported that, differently from ALK and RET, high wild-type ROS1 endogenous expression in normal tissue may obscure ROS1 3′/5′ EI detection in the tumor counterpart." (PMID 36612287, 2022). "Subsequent identification of ALK rearrangements and several cancer‐driver events, including ROS1, NRG1, NTRK1/RET fusion, BRAF (V600E) mutation, or MET amplification/Exon14 skipping, strengthened the concept of oncogene addiction and tumor heterogeneity as a pillar of modern cancer therapeutics." (PMID 35838331, 2022). "The tumor-specific DNA markers including point mutations in EGFR or BRAF genes, rearrangements involving ALK or ROS1 genes and fusions of NTRK1/2/3 genes along with tumor mutation burden (TMB) and PDL-1 RNA expression serve as guides in proper therapy selection." (PMID 35837614, 2022). "For NSCLC, activation of EGFR, ALK, ROS-1, and other targetable genes in the tumor are evaluated." (PMID 35806042, 2022). "We performed IHC and found that ROS1 was diffusely positive in the tumour." (PMID 34396843, 2021). "Additionally, ROS1 amplifications have been reported in soft-tissue sarcomas, breast cancer and many other tumor types." (PMID 34884672, 2021). "Recently larotrectinib, a pan-TRK inhibitor, and entrectinib, a pan-TRK, ALK, and ROS1 tyrosine kinase inhibitor, were the first tumor-agnostic-targeted therapies developed and approved in oncology for the treatment of pediatric and adult tumors that have an NTRK gene fusion." (PMID 32087721, 2020). "This evidence suggests a possible role for ROS1 inhibitors in the treatment of patients with E‐cad‐defective tumours and may represent a foundational element for future ad hoc translational studies and clinical trials." (PMID 32301282, 2020). "Molecular aberrations involving various driver mutations including ALK, ROS1, KRAS, IDH1/2 and JAK2 may impact thrombotic risk in various tumor types." (PMID 32707653, 2020).
tumor (continued). "Since our IPM is based on tumor microenvironment-related genes, although its establishment is related to EGFR mutation, ALK translocation, ROS1 translocation, and BRAF mutation, it is applicable to all patients with or without these mutations in stage I-II LUAD." (PMID 33585210, 2020). "Clinicopathological characteristics, driven genes’ status (EGFR, ALK, and ROS1), adjuvant chemotherapy strategy for 94 surgical resected LCNECs were extracted from digital database, tumor relapse or progression, and survival were analyzed with clinical profiles." (PMID 33335851, 2020). "The development of molecularly targeted therapies, as well as ICIs, has improved outcomes in the metastatic setting for NSCLC patients who harbor somatically activated oncogenes such as EGFR and BRAFV600, rearranged ALK or ROS1, or PD-L1 expression ≥50% of tumor cells." (PMID 30818873, 2019). "For NSCLC, NGS-based tumor-profiling multiplex gene panels, such as Oncomine Dx target test or FoundationOne CDx, have recently been approved as companion diagnostics to detect mutations of EGFR and BRAF, or fusions of ALK and ROS1 in the US." (PMID 30943926, 2019). "ROS1 rearrangement has been firstly reported in an adult glioblastoma tumour." (PMID 29455670, 2018). "Compared to the macrophages in WT group samples, the macrophages isolated from PKN2-WT tumor showed significantly higher expression of Il1b, Tnf, Cxcl9, Il23, Ros1 and Il12b and significantly lower expression of Tgfb1, Vegfa, Egf, Retnla and Il10, illustrating predominant M1 phenotype." (PMID 29368606, 2018). "Thus, the frequency of tumor-tissue EGFR M- and plasma cfDNA EGFR M+ patients is 4.0% (155/3834), which is higher than the frequencies of tumor tissue rare mutations such as ROS1, RET, BRAF, etc." (PMID 28052016, 2017). "Elevation of ROS1 protein levels in tumour cells may be detected by immunohistochemistry (IHC) using antibodies against ROS1 protein." (PMID 27535289, 2016). "Of all ROS1-rearranged cases, only 1 sample was material from total tumor resection lobectomy." (PMID 25868855, 2015). "It is uncertain that ROS1 rearrangement may represent a potentialnew therapeutic opportunity for now, but biomarker discovery efforts should be continued to develop molecular tumor classification and to improve outcome and management of patients with GBM." (PMID 26366867, 2015). "Therefore, for patients with ROS1 fusions, initiating anti‐tumor therapy as soon as possible to reduce tumor burden may decrease the risk of TEs." (PMID 40751559, 2025). "Repotrectinib is a newer ROS1 TKI that is considered less susceptible to ROS1 resistance mechanisms among patients with ROS1+ aNSCLC and more active in the CNS; deep reductions in tumor volume and durable clinical activity have been observed, including in brain lesions." (PMID 40075596, 2025). "The case of a CD74-ROS1 fusion in a 64-year-old inflammatory breast cancer patient (IBC) was found through NGS as a combination of CD74 exon 7 and ROS1 exon 34, which may have contributed to rapid disease progression as they died 18 months after tumor discovery." (PMID 37958963, 2023). "Moreover, iruplinalkib showed robust antitumor effects in BALB/c nude mice xenograft models with ALK-/ROS1-positive tumors implanted subcutaneously, and the tumor suppressive effects in crizotinib-resistant model was significantly better than that of brigatinib." (PMID 37036582, 2023). "Specifically, these mutations are located on five tumor suppressors (SDHA, RB1CC1, PTCH1, DMBT1, BCR) and eight proto-oncogenes (MERTK, CSF1R, MYB, ROS1, PCM1, FGFR2, MYH11, BRCC3) and have an allele frequency lower than 0.01 in the Genome Aggregation Database (GnomAD)." (PMID 33466296, 2021).
tumor (continued). "For NSCLC in particular, different studies have shown that TMB in the primary tumour tends to be higher in men than in women and is also positively correlated with tobacco consumption, KRAS, and BRAF mutated tumours, whereas the presence of ROS1 and ALK rearrangements is linked to lower TMB." (PMID 34683113, 2021). "We examined whether high PD-L1 expression, tumor mutational burden (TMB), and presence of targetable mutations (EGFR, BRAF, ERBB2, RET or ALK translocations, ROS1 rearrangements) occur at different frequencies in tumors from black patients compared to non-black patients." (PMID 31645901, 2019). "With IHC, ROS1 protein expression may also be detected in normal cells, namely histiocytes/giant cells, reactive type II pneumocyte hyperplasia and bronchiolar metaplasia at the tumour periphery or in subpleural areas." (PMID 27535289, 2016). "Further studies are necessary to elucidate whether ROS1 is also implicated in tumor progression of some ROS1-non-rearranged tumors and whether its expression could be affected by smoking." (PMID 25058391, 2014). "We employed targeted next-generation sequencing to analyze seven actionable driver genes - EGFR, KRAS, NRAS, BRAF, ALK, ROS1, and PIK3CA - in formalin-fixed, paraffin-embedded tumor specimens from Vietnamese NSCLC patients." (PMID 40502411, 2025). "Other potential limitations include assessing for pLoF in oncogenic candidates such as RET, ROS1, FGFR4, and MYC, while FAT1 and LEF1 reported to oscillate between oncogenic and tumour suppressive behaviour." (PMID 41038821, 2025). "None of the included NSCLC patients bared targetable genetic tumor alterations (EGFR, ALK, or ROS1)." (PMID 40091413, 2025). "Among these, IMT is a common type of intermediate (locally aggressive) tumor composed of myofibroblasts, frequently harboring ALK or ROS1 fusions." (PMID 40242239, 2025). "One week later, the NGS results revealed that the tumor harbored an EZR-ROS1 rearrangement, which was further confirmed by positive ROS1 immunohistochemical staining." (PMID 41515905, 2025). "It has been widely used to detect druggable tumor-specific genes such as EGFR, ALK, ROS1, BRAF, KRAS, NTRK1/2/3, ERBB2, RET, and MET in patients with NSCLC." (PMID 41515905, 2025). "This can be explained by the low prevalence of ROS1 rearrangements across NSCLC patients; which restricts the access to the substantial amount of tumor specimens required to conduct solid studies." (PMID 39737401, 2024). "Overall, 16% of the tested tumours (4/25) harboured oncogenic fusion genes and we identified TMEM106B::ROS1 as a new fusion gene for CCA." (PMID 38877653, 2024). "ROS1 rearrangements occur in about 1–2% of NSCLC cases, leading to the expression of oncogenic ROS1 fusion proteins that drive tumor growth." (PMID 39064229, 2024). "From The Cancer Genome Atlas (TCGA) and the Gene Expression Omnibus (GEO) databases, all available ROS1+ (n = 10), ALK+ (n = 5) and RET+ (n = 5) NSCLC tumor and ROS1+ cell line (n = 7) RNA-sequencing files were collected." (PMID 39737401, 2024). "APG-2449 is a triple kinase inhibitor of ALK, ROS1, and FAK that has shown anti-tumor activity in a mouse model of ALK/ROS1-positive NSCLC." (PMID 38474400, 2024). "The findings highlight the complex interplay between genomic alterations, the tumor immune microenvironment, and clinical outcomes in ALK/RET/ROS1-rearranged NSCLC using NGS." (PMID 38397899, 2024). "Strong antitumor effects have been demonstrated in tumor xenograft models derived from genetically engineered cells overexpressing ALK rearrangements, ROS1+ rearrangements, or crizotinib-resistant ALK and ROS1 mutations, as well as in CNS tumor models." (PMID 39081957, 2024). "The agnostic use of ROS1 inhibitors was considered in the NCI-MATCH investigation; however, only one out of four recruited patients experienced an objective tumor response." (PMID 38612902, 2024).